INS (insulin)
Diseases named in the same sentence as INS in open-access papers (continued):
Sharing a sentence is not in itself a finding about the gene and the disease.
hypothyroidism (continued). "Plasma insulin levels during the test tended to be higher in women with hypothyroidism than in the healthy subjects until the end of the test but the differences were not significant." (PMID 24711817, 2014). "In fact, insulin levels even increased in the group with hypothyroidism when in the control group they had already fallen." (PMID 24711817, 2014). "The correlation between resistance to insulin and hypothyroidism has been given significant attention for decades and extensive studies have been carried out in this regard." (PMID 25114670, 2014). "Mean values of glucose and insulin areas under the curve were higher in women with hypothyroidism than in control group (286.79 ± 23.65 versus 188.41 ± 15.84 mmol/L·min, P < 0.003 and 7563.27 ± 863.65 versus 4987.72 ± 583.88 mU/L·min, P < 0.03 resp)." (PMID 24711817, 2014). "In contrast, studies showed that, in hypothyroidism, there is a decrease in both glucose disposal and insulin mediated-glucose uptake in muscle, and also an impaired ability of insulin to stimulate glucose disposal related to insulinaemia." (PMID 25105294, 2014). "An enhanced dose of insulin is required to ameliorate hypothyroidism, but the therapy warrants caution for adrenal or pituitary failure." (PMID 23671867, 2013). "In hypothyroidism, there is a reduction in glucose-induced insulin secretion by beta cells, and the response of beta cells to glucose or catecholamine is increased in hyperthyroidism due to increased beta cell mass." (PMID 23671867, 2013). "They demonstrated that hypothyroidism induced a decrease in the insulin-mediated glucose disposal that reverted upon treatment." (PMID 21941681, 2011). "This impairment in the ability of insulin to increase blood flow rate to the hypothyroid tissues is an alternative explanation to the mechanism whereby hypothyroidism can induce lower glucose disposal." (PMID 21941681, 2011). "The highest risk was observed among non-insulin-treated diabetics, particularly those without thyroid dysfunction or with hypothyroidism." (PMID 41153651, 2025). "The blood levels of metabolic hormones, including adipokines (insulin, adiponectin, leptin, apelin, chemerin, resistin, visfatin, vaspin, and omentin), in patients with thyroid dysfunction (hyperthyroidism and hypothyroidism) and correlations between thyroid and metabolic hormones." (PMID 40563510, 2025). "Notably, the treatment of hypothyroidism has been shown to improve insulin sensitivity, emphasizing the crucial role that thyroid hormones play in glucose metabolism." (PMID 39831884, 2025). "On the other hand, in hypothyroidism, the insulin resistance of peripheral tissues prevails." (PMID 40731899, 2025). "The results of the study indicated that there was no causal effect of hypothyroidism on 2-hour glucose (p = 0.836), fasting glucose (p = 0.419), and fasting insulin (p = 0.268)." (PMID 39403577, 2024). "Overall, the data here reported suggest that the hepatic hypothyroidism detected in F2-exposed males could simulate a fasting condition although insulin signaling is activated." (PMID 37298533, 2023). "In particular, in the presence of subclinical or overt hypothyroidism, muscle and adipose tissue become resistant to insulin, with a reduced insulin-stimulated glucose uptake in these tissues due to impaired translocation of GLUT4 glucose transporters on the plasma membrane." (PMID 37024642, 2023). "In people who have DM and hypothyroidism and are treated with insulin, an adjustment in insulin dosage might be needed." (PMID 38004062, 2023). "Insulin and hypothyroidism were chosen to assess a newerhypothesis that metabolic syndromes may play a significant role in the onsetrisk or outcome of AD." (PMID 35936510, 2022).
hypothyroidism (continued). "Medication use investigated in this study comprises large medication groups such as blood pressure medications and other heart disease medications (e.g., nitroglycerin, antiarrhythmics, anticoagulants) along with more specific medications such as insulin and hypothyroidism medication." (PMID 36434564, 2022). "Furthermore, insulin-stimulated glucose transport was reported to decrease in patients with hypothyroidism due to disrupted translocation of GLUT4 on the plasma membrane." (PMID 35740085, 2022). "For patients with hypothyroidism, most patients will have positive thyroid peroxidase antibody, TH decreased and abnormal immune function, which will further affect the utilization of insulin in peripheral tissues." (PMID 35419407, 2022). "However, the evaluation using the metabolic euglycemic clamp reveals a subtle effect of the treatment of hypothyroidism on the increase in insulin sensitivity." (PMID 34880913, 2021). "Additionally, according to a study, in hypothyroidism due to decreased insulin clearance by the kidneys, the physiological need for insulin was decreased." (PMID 35106234, 2021). "The pathogenesis of elevated RBP-4 in hypothyroidism is generally attributed to the role of adipose tissue as an endocrine organ capable of secreting a number of adipose-tissue-specific hormones that are involved in the regulation of insulin action." (PMID 33133591, 2020). "Previous studies on isolated islets from male rat offspring showed that maternal hypothyroidism led to impaired insulin secretion through a combination of different mechanisms, including alteration in glycolytic pathways and ATP sensitive K+ (KATP) and L-type Ca2+ channel conductance." (PMID 32472193, 2020). "Similarly, hypothyroidism was detected in twenty-one percent 21 (21%) of the patients whereas fasting serum insulin was found to be raised in thirty-three percent 33 (33%) of the total subjects." (PMID 34506401, 2020). "One study found that women with severe hypothyroidism showed lower insulin sensitivity." (PMID 32481623, 2020). "Recently, the relationship between maternal hypothyroidism and glucose metabolic abnormalities in adult offspring has been increasingly emphasized, with research in rats showing that maternal hypothyroidism causes IUGR and diminished insulin secretion capacity in adult offspring." (PMID 30918900, 2019). "In hypothyroidism, there is a slow glucose gastrointestinal absorption, retardation of gluconeogenesis, and glucose utilization peripherally with a consequent increase of insulin resistance." (PMID 29214182, 2017). "The effects of hypothyroidism on development of the fetal endocrine pancreas may be mediated indirectly by other hormones, such as insulin, leptin and IGFs." (PMID 28144955, 2017). "This suggests that histological changes in endocrine pancreas induced by hypothyroidism could occur before insulin and glucose alteration." (PMID 26175757, 2015). "Moreover, small islets secrete more insulin than large islets, and small islets are more resistant to the impact of hypothyroidism on their morphometric characteristics because of their high proliferation." (PMID 26175757, 2015). "Although the insulin secretion deficit in hypothyroid male rats has been documented, the underling mechanisms of the effect of hypothyroidism on insulin secretion are not clear." (PMID 26132582, 2015). "Thyroid hormones have the ability to increase the mobilization of stored triglycerides by stimulating adipose tissue lipolysis, although there remain areas of uncertainty regarding the interplay between insulin action and adipose tissue lipolysis in hypothyroidism." (PMID 25690422, 2015). "Nevertheless, the underlying mechanisms of the effect of hypothyroidism on insulin secretion are not yet clear." (PMID 26132582, 2015). "Both hypothyroidism and hyperthyroidism affect insulin sensitivity." (PMID 24711817, 2014).
hypothyroidism (continued). "Calculated areas under the curves of blood glucose and plasma insulin in the OGTT were significantly higher in women with hypothyroidism than in women without thyroid hormone deficiency." (PMID 24711817, 2014). "Therefore, one possible explanation to decreased insulin responsiveness in hypothyroidism, according to the authors of this study, includes a dysregulation of leptin action at the hypothalamus." (PMID 21941681, 2011). "With regards to hypothyroidism, cases of hypoglycemia have been reported in the literature despite the fact that peripheral insulin resistance may be present." (PMID 21941681, 2011). "Additionally, hypothyroidism significantly impacts glucosemetabolism by reducing insulin sensitivity, impairing hepatic glucose production and peripheral glucose uptake, ultimately contributingto insulin resistance a key driver of NAFLD pathogenesis." (PMID 41393433, 2025). "However, for individuals with thyroid dysfunction, diminished insulin signaling may further impair T3 production and exacerbate hypothyroid symptoms." (PMID 41020818, 2025). "However, the study did find that exposed mice were more likely to be glucose-intolerant and insulin-resistant on high-fat diets, suggesting that offspring born to mothers with hypothyroidism may be more vulnerable to metabolic stress." (PMID 39090558, 2024). "Importantly, hypothyroidism alters how fat cells react to insulin." (PMID 37626767, 2023). "In this study, insulin secretion, thyroid hormone synthesis and the thyroid hormone signaling pathway were also co-enriched, and it showed the effects of Lactobacillus rhamnosus hsryfm 1301 fermented milk on hyperinsulin secretion and hypothyroidism induced by high-fat diet." (PMID 36432537, 2022). "Indeed, albeit more certain for hypothyroidism, multiple reports revealed discrepant results about the contribution of thyrotoxicosis to the occurrence of insulin resistance, primarily inducing hepatic glycogenolysis and downregulating hepatic glycogen synthesis." (PMID 36676947, 2022). "Moreover, anorectic circumstances may also contribute to lower insulin production in hypothyroidism." (PMID 35106234, 2021). "Furthermore, patients in therapy with insulin were significantly more affected by chronic hypertension (0.5 vs 3.2%, p < 0.001) and hypothyroidism (6.1 vs 9.9%, p 0.002), and their pregnancy was more likely achieved using assisted reproductive technology (ART) (4.2 vs 7.3%, p 0.003)." (PMID 33767671, 2021). "From studies both in vivo and in vitro, the effects of hypothyroidism on pancreatic beta cell proliferation and mass before birth appear to be due not only to the deficit in circulating thyroid hormones, but also to coincident changes in insulin and leptin exposure." (PMID 28144955, 2017). "Additionally, insulin clearance may be diminished in hypothyroidism coinciding with higher levels of counter-regulatory hormones, i.e., cortisol, glucagon, growth hormone and adrenalin." (PMID 25690422, 2015). "Similar to previous data, results of this study confirm that hypothyroidism reduces glucose stimulated insulin secretion in rats, a finding that may be due to abnormality in some parts of glucose sensor apparatus of the beta cells, including GLUT2 protein levels and glucokinase specific activity." (PMID 26132582, 2015). "Anorectic conditions in hypothyroidism may also contribute to reduced insulin in this state." (PMID 23671867, 2013). "Under the KD where insulin and leptin levels are suppressed and deiodinase stimulation is reduced, individuals with the Ala/Ala or Thr/Ala genotype may be particularly vulnerable to functional intracellular hypothyroidism, even when serum TSH and T4 appear normal." (PMID 41020818, 2025). "A positive, strong correlation was observed with metformin treatment, whereas other parameters showed moderate (TG, insulin, BMI, waist circumference, S100B, and LEP) and weak (hypothyroidism and VIS_E) positive correlation." (PMID 37960185, 2023).
hypothyroidism (continued). "Regular physical activity helps maintain optimal body weight, enhance insulin sensitivity, enhance BMR, and release endorphins, which aid in menstrual cycle regularisation, PCOS and hypothyroidism improvement, PMS reduction, and overall well-being." (PMID 35739585, 2022). "In hypothyroidism, RBP4 correlated positively with the lipid profile, fasting glucose, insulin and HOMA-IR, while in Hashimoto thyroiditis it correlated with insulin and HOMA-IR." (PMID 35448487, 2022). "In patients with hypothyroidism, impaired translocation of GLUT4 glucose transporters contributed to decreased insulin-stimulated rates of glucose transport." (PMID 34017311, 2021). "In subjects with sub-clinical hypothyroidism, CRP has been found to be positively related to insulin and higher than in control subjects with normal thyroid function." (PMID 19014658, 2008). "Insulin requirements at discharge were notably higher in children with celiac disease (P = 0.031), while no significant disparities were observed based on age, sex, presence of DKA, or hypothyroidism." (PMID 42005131, 2026). "This study emphasises the efficacy of METS‐IR as a diagnostic tool for IR in patients with hypothyroidism, establishing it as a comprehensive alternative to HOMA‐IR rather than HbA1c and non‐based insulin level." (PMID 40445873, 2025). "This may result from the complex relationship between insulin resistance indices and thyroid-stimulating hormone (TSH) levels, explained by the tendency of hypothyroidism to increase adiposity and pro-inflammatory markers." (PMID 40612820, 2025). "As no statistical difference was found between hypothyroidism and 2-hour glucose, fasting glucose and fasting insulin." (PMID 39403577, 2024). "Serum fructosamine concentration, insulin dose and insulin resistance index (IRI) were assessed before the diagnosis (t0) of the concurrent disease (hypercortisolism or hypothyroidism), and after 1 month (t1) and 3 months (t2) of trilostane or levothyroxine treatment." (PMID 39535393, 2024). "In contrast, in patients with T2DM and hypothyroidism, LT4 replacement may reduce insulin levels and improve endogenous insulin secretion; thus, a lower dose of insulin should be considered after normalization of thyroid function." (PMID 38004062, 2023). "In detail, the subclinical and overt hypothyroidism has far been demonstrated promoting obesity, low-density lipoprotein (LDL) and cholesterol accumulation as well as diastolic and systolic blood pressure increase and insulin resistance." (PMID 36676947, 2022). "In spite of the hypervascularization and immune cells infiltration in pancreas of female rabbits, we previously showed that neither insulin nor glucose levels are affected by hypothyroidism." (PMID 26175757, 2015). "Thus, despite increased gluconeogenesis in hyperthyroidism, and enhanced glucose-stimulated insulin secretion in overt hypothyroidism and SCH, plasma glucose levels tend to be higher in hypothyroidism." (PMID 25690422, 2015). "Insulin tolerance was not significantly affected by hypothyroidism." (PMID 36143246, 2022). "However, insulin and HOMA-IR values were lower in the young patients with hypothyroidism." (PMID 34946319, 2021). "As opposed to compelling research indicating the association of DM and thyroid dysfunction, which is supported by the well‐described role of THs on glucose metabolism and insulin secretion, other studies have failed to link hypothyroidism to the development of T2DM." (PMID 33048427, 2020). "Studies showed that smoking and IR may impact the actions of subclinical hypothyroidism on the lipid profile, and that defective insulin mediated lipolysis is suppressed in mild hypothyroidism, but not in severe hypothyroidism." (PMID 32824723, 2020). "However, constant low levels of insulin synthesis and cell proliferation in offspring after birth are not likely to be due to transient subclinical hypothyroidism." (PMID 30918900, 2019).
hypothyroidism (continued). "Lack of experiments on the human isolated islets insulin secretion in hypothyroidism is apparent but literature review reveals that all studies on animal isolated islets report impaired and not increased insulin secretion in response to glucose in hypothyroidism." (PMID 26132582, 2015). "Effects of hypothyroidism on insulin secretion have not been clearly elucidated." (PMID 26132582, 2015). "It is worth mentioning that enhanced insulin response is only observed in some homeostatic models or glucose tolerance tests while all studies in isolated islets including our current one have documented impaired and not increased insulin secretion in hypothyroidism." (PMID 26132582, 2015). "However, D2 activities were very low and were not influenced by hypothyroidism, fasting or insulin." (PMID 25277744, 2014).